MMP8 (matrix metallopeptidase 8)
Diseases named in the same sentence as MMP8 in open-access papers (continued):
Sharing a sentence is not in itself a finding about the gene and the disease.
Peri-Implantitis (continued). "In the same study, the matrix metalloproteinase‐8 (MMP-8) demonstrated a trend similar to IL-1β, elevated in peri-implantitis and correlated with clinical parameters, such as bleeding on probing and increased probing depth." (PMID 36997949, 2023). "The screening of MMP-8 can help in the early stages of peri-implant mucositis and peri-implantitis, allowing for quick therapeutic intervention." (PMID 37232785, 2023). "As MMP-1 and MMP-8 are mainly responsible for collagen matrix destruction in peri-implantitis, the MMP-1/TIMP-1 and MMP-8/TIMP-1 ratio shifts in favor of MMPs can serve as an indicator of peri-implantitis progression and inefficiency of treatment." (PMID 37232785, 2023). "As one of the major proteases in GCF, MMP-8 plays a vital role in the initiation and progression of peri-implantitis and shows a relationship with various clinical indicators." (PMID 37371608, 2023). "Previous studies suggested a cutoff a-MMP-8 value of < 20 ng/mL to differentiate peri-implantitis sites from clinically healthy sites." (PMID 36359443, 2022). "In peri-implantitis, access flap debridement alone can significantly reduce some investigated biomarkers (MMP-8 and TNF-a) in the long-term (12 months after surgery)." (PMID 36360962, 2022). "This led to the development of point-of-care tests using MMP-8 as a reference test for grading peri-implantitis." (PMID 35163727, 2022). "MMP-8 levels were previously reported to be increased in PICF from sites with peri-implantitis, and MMP-8 levels in PICF from peri-implant disease sites correlated with GI scores (ρ = 0.772, P < 0.001)." (PMID 30209708, 2018). "The level detected in the peri-implant sulcus fluid of the active form of matrix metalloproteinase-8 (MMP-8), which rises in the case of peri-implantitis, was also found to differ significantly between titanium and ZrN abutment surfaces in vivo." (PMID 29944716, 2018). "There are some studies that have measured MMP-8 in implant sulcus fluid, GCF and saliva but there is a gap in knowledge based on the utility of a POC oral fluid MMP-8 test for chair-side diagnostics of peri-implantitis." (PMID 28117682, 2017). "The presence of MMP-8 in PISF obtained from patients with peri-implantitis or mucositis has been observed by many authors." (PMID 28757684, 2017). "Levels of IL-1β and MMP-8 were significantly elevated in implants with peri-implantitis." (PMID 36997949, 2023). "MMP-8 clearly leads the way in peri-implantitis screening and even grading." (PMID 37232785, 2023). "Such correlation also happened between PGLYRP1 and MMP-8 in the mucositis peri-implantitis groups." (PMID 35329310, 2022). "High levels of oral fluid MMP-8 in subjects with clinically “appearing” healthy periodontium/peri-implantium indicate silent “hidden,” developing future preperiodontitis and pre-peri-implantitis indicating early preventive supportive periodontal and peri-implant treatment." (PMID 30305812, 2018). "Our observation might imply that monitoring of MMP-8 level in PISF could help to diagnose mucositis/peri-implantitis in an early stage, prior to clinical manifestations, which may allow for quick start of appropriate therapy." (PMID 28757684, 2017). "In peri-implantitis lesions, MMP-8 is a major destructive collagenase and results from previous studies showed that MMP-8 in oral fluids could have predictive value." (PMID 28117682, 2017). "Moreover, the determination of a-MMP-8 levels in PISF has been shown to be useful for screening susceptible sites and patients, differentiating peri-implant sites, and evaluating the progression of bone loss in peri-implantitis." (PMID 36359443, 2022). "Thus, our observation might imply that monitoring of MMP-8 level in PISF could help to diagnose mucositis/peri-implantitis in an early stage, prior to clinical manifestations, which may allow for quick start of appropriate therapy." (PMID 28757684, 2017).
Peri-Implantitis (continued). "In peri-implantitis, IL-6, IL-1β, TNF-α, MMP-8, and their genetic variations appear to be the most important cytokines not only in pathogenesis but also in their potential diagnostic capabilities." (PMID 41172495, 2025). "Studies indicate that biomarkers like Matrix metalloproteinase 8 (MMP-8) and Interleukin1β (IL-1β) can be helpful in detecting peri-implantitis in the peri-implant sulcus fluid (PISF)." (PMID 39917223, 2024). "Peri implant mucositis shows significantly increased levels of IL-1β, aMMP8, procalcitonin, bone turnover marker RANKL and salivary alpha amylase while IL-1β, VEGF, MMP8, Procalcitonin, RANKL, Osteoprotegerin (OPG) are all significantly elevated in peri implantitis." (PMID 41584075, 2025). "This suggests that 24 ng/mL is the most effective cutoff value for distinguishing between individuals with and without peri-implantitis based on MMP-8 levels." (PMID 39657936, 2025). "Thus, we show that salivary IL-1β, MMP-8 and TNF-α show strong potential as reliable, non-invasive biomarkers for early detection and monitoring of peri-implantitis." (PMID 41907937, 2025). "Statistical analysis (t-tests and correlations, p < 0.05) revealed significantly elevated levels of IL-1β, MMP-8 and TNF-α in peri-implantitis patients, with IL-1β and MMP-8 strongly correlating with probing depth and TNF-α moderately correlating with bone loss." (PMID 41907937, 2025). "MMP-8 was also detected in the PISF of patients not affected by peri-implant mucositis or peri-implantitis, although the level of this marker was always lower than in the PISF collected from peri-implant mucositis/peri-implantitis patients." (PMID 35055373, 2022). "Thus, in addition to aMMP-8, MMP-8 per TIMP-1, PMN elastase and MPO, seem to be possible alternatives for BOP as more accurate indicators of peri-implant tissue destruction and peri-implantitis." (PMID 32764436, 2020). "Both PMN- and non-PMN-type MMP-8 isoforms particularly in active forms have been observed in PISF of peri-implantitis patients." (PMID 30305812, 2018). "In our study, we have proved the presence of MMP-8 in PISF obtained from individuals without clinical symptoms of developing mucositis or peri-implantitis." (PMID 28757684, 2017). "Therefore, it is of interest to evaluate the diagnostic efficacy of salivary biomarkers-interleukin-1β (IL-1β), matrix metalloproteinase-8 (MMP-8) and tumour necrosis factor-alpha (TNF-α)-by comparing their concentrations in patients with healthy peri-implant tissues and those with peri-implantitis." (PMID 41907937, 2025). "It is noteworthy that aMMP-8 is not synonymous to total MMP-8 in peri-implantitis diagnosis." (PMID 41358008, 2025). "Interestingly, MMP-8 was also detected in PISF of patients not affected by mucositis or peri-implantitis, although the level of this marker was always lower than in PISF collected from mucositis/peri-implantitis patients." (PMID 28757684, 2017). "Some data imply that MMP-8 level in PISF might be useful for evaluating the condition of peri-implant tissues and monitoring a development of peri-implant inflammation—mucositis or peri-implantitis." (PMID 28757684, 2017). "Some data imply that Metalloproteinase-8 (MMP-8) level examination in peri-implant sulcular fluid (PISF) might be useful for evaluating the condition of peri-implant tissues and monitoring a development of peri-implant inflammation, including both mucositis and peri-implantitis." (PMID 28757684, 2017). "During the treatment of peri-implant mucositis and peri-implantitis there were minimal effects of non-surgical treatment alone on the investigated inflammatory biomarkers (IL-4, IL-10, and IL-12, TNF-a, RANKL, OPG IL-1β, IL-6, TNF-α, MCP-1/CCL2, MIP-1α/CCL3, IFN-γ, MMP-8, sRANKL, OPG and G-CSF)." (PMID 36360962, 2022).
diabetes (43 papers, 2012 to 2025). "MMP-3 and MMP-8, besides being involved in periodontal pathology, are also associated with cardiovascular pathology and diabetes." (PMID 36830029, 2023). "Metabolic syndrome and diabetes (often a result of the former) have been associated with COVID‐19‐related adverse outcomes, and both these conditions have been linked with elevated MMP‐8 levels." (PMID 35818743, 2022). "Increased MMP-8 levels in association with diabetes have earlier been shown in saliva, gingival crevicular fluid and in gingival tissues." (PMID 23637817, 2013). "Increased concentrations of MMP-8 have been associated with an increased inflammatory process in patients with diabetes." (PMID 23637817, 2013). "Additionally, MMP‐8 and its impact on the process of wound healing appear to be associated with hindered wound healing and other vascular issues in individuals with diabetes, which is a significant concern for public health." (PMID 38433295, 2024). "The expression of MMP-8 in gingival tissues and oral fluids can also be upregulated by the development of diabetes from metabolic syndrome via prediabetes." (PMID 40299548, 2025). "MMP-8 also accelerates the progression of diabetes by cleaving and deactivating the insulin receptor." (PMID 40299548, 2025). "Results of a meta-analysis of eight studies on the possible role of MMP-8 in the pathogenesis of PD in patients with diabetes revealed that there are higher levels of MMP-8 in patients with PD compared to those without PD." (PMID 38614881, 2024). "This study gives an additional argument in favor of MMP8 inhibition to potentially decrease/reverse insulin resistance and diabetes in obese patients." (PMID 37445827, 2023). "Previous studies have shown that MMP-1 and MMP-8, in addition to being intensively involved in periodontal pathology, are also strongly correlated with cardiovascular pathology and diabetes." (PMID 35163727, 2022). "MMP‐8 brings about human insulin receptor protein cleavage which in turn results in insulin resistance and consequently, diabetes mellitus." (PMID 35818743, 2022). "In our study, similarly to many others, we used the GCF as a tool to analyse the locally derived biomarkers related to periodontal inflammation (IL‐8, MMP‐8) and diabetes (AGEs)." (PMID 33369174, 2021). "In the DG, diabetes decreased the expression levels of MMP-8 and MMP-9 induced by mandibular advancement and increased the expression levels of TIMP-1 compared with that of the NG." (PMID 25289023, 2014). "Experimental diabetes significantly decreased the ratio of MMP-8 to TIMP-1 and MMP-9 to TIMP-1 compared with that of the NG (P<0.05)." (PMID 25289023, 2014). "MMP-8 levels were elevated in saliva from patients after cardiac surgery or suffering from diabetes, and muscle and joint diseases." (PMID 23637817, 2013). "Besides, hypertension and diabetes are linked by CXCL8, HLA-B, and KANSL1; diabetes and obesity are linked by TRIM26 and MMP8; hypertension and obesity are linked by PLA2G7, FSTL3, STC2, and BCL2A1." (PMID 36685671, 2023). "Interestingly, early decrease of circulating MMP8 levels was recently demonstrated to correlate with leptin reduction and predict diabetes remission in patients that underwent bariatric surgery at a 3-year follow-up timepoint." (PMID 37445827, 2023). "Patients with diabetes had higher concentrations of MMP-8 and a higher MMP-8/TIMP-1 ratio." (PMID 23637817, 2013). "Additionally, it is important to consider diverse patient populations characterized by various factors such as smoking habits, diabetes status, and dietary practices, including snacking frequency, all of which may influence MMP-8 levels." (PMID 40045958, 2025). "CVD, diabetes, hypertension, and cancer did not associate significantly with MMP-8." (PMID 39917664, 2024). "When we compared patients with CVD or diabetes to the healthy reference group in the whole study population, we found that CVD and diabetes patients had lower MMP-8 levels than the healthy." (PMID 39917664, 2024).
diabetes (continued). "Furthermore, it has been reported that patients with diabetes mellitus (DM) exhibit higher concentrations of MMP-8 in their saliva, which is thought to enhance enzymatic activity and contribute to the weakening of the dentin–resin interface." (PMID 39852560, 2024). "MMP-8 concentration was lower in individuals with CVD (p = 0.004) and in those with prevalent diabetes (p = 0.01)." (PMID 39917664, 2024). "High levels of MMP-2, MMP-3, MMP-8 and MMP-9 have been found in the epithelium and stroma of melted and perforated corneas after topical NSAID use and in patients with diabetes." (PMID 38528481, 2024). "In conclusion, our study found that MMP8 and MMP9 are upregulated in the knee cartilage of diabetes-induced OA rats." (PMID 33468174, 2021). "In contrast, interfering with the expression of MMP8 and MMP9 alleviated the cartilage damage in diabetic OA rats." (PMID 33468174, 2021). "Numerous studies in the literature have shown that MMPs (such as MMP-2, MMP-7, MMP-8, MMP-9, MMP-14) register altered values in patients with DM (types 1 and 2) and this seems to contribute to several complications of diabetes." (PMID 34829612, 2021). "We examined the effect of MMP8 and MMP9 expression intervention on the number of diabetic OA knee chondrocytes." (PMID 33468174, 2021). "MMP8 and MMP9 aggravate the injury of the knee joint cartilage and promote the apoptosis of articular chondrocytes in diabetes-induced OA rats." (PMID 33468174, 2021). "Of note, the IHC results showed that the number of MMP8- and MMP9-positive cells was significantly increased in the knee joint cartilage of the diabetic OA rats (p < 0.01)." (PMID 33468174, 2021). "The results of the present study support this data and identified that mandibular advancement increases MMP-8 expression levels and the ratio of MMP-8 to TIMP-1 in condylar cartilage, while diabetes downregulates this augmentation." (PMID 25289023, 2014). "Patients with diabetes had a three times higher ratio of MMP-8/TIMP-1 and twice as high concentration of MMP-8." (PMID 23637817, 2013). "Patients with comorbidities such as hypertension, obesity, and diabetes had elevated DPPIV, MMP-8, and TIMP-4 levels, and reduced MMP-3 and TIMP-2 levels, indicating a link between these markers and the exacerbating effects of comorbidities on COVID-19 outcomes." (PMID 40557167, 2025). "In patients with CKD and diabetics, serum levels of MMP-2, MMP-8, and MMP-9 were found to be higher, being correlated with serum phosphate (MMP-2), fibroblast growth factor-23 (FGF-23), and proteinuria (MMP-8 and MMP-9), which are both associated with oxidative stress and cardiovascular health." (PMID 37840653, 2023). "We found the MMP-8 levels in LT recipients with diabetes to be higher than in recipients with no diabetes, although the difference was statistically non-significant." (PMID 33916950, 2021). "However, in the diabetic OA and the MMP8 and MMP9 overexpressing group (Diabetic OA-OE), matrix staining was weakened and unevenly distributed." (PMID 33468174, 2021). "In this study, we found that MMP8 and MMP9 were upregulated in the knee joints of diabetic OA rats." (PMID 33468174, 2021). "After adjusting for potential confounders including age, sex, BMI, diabetes, hypertension, lung disease, AF and CKD, these differences (or similarities) in plasma biomarkers between HFpEF and HFrEF persisted with the exception of MMP-8." (PMID 32349122, 2020). "We hypothesize that MMP8 and MMP9 may play an important role in the pathogenesis of diabetic OA." (PMID 33468174, 2021). "Additionally at day 6, the time when the most prominent diabetes related changes in PVC implant inflammatory cell neutrophil markers (NGAL and MMP-8) were observed, there was a parallel increase in the expression of these markers of peripheral blood neutrophils." (PMID 28182694, 2017).
breast carcinoma (38 papers, 2006 to 2026). "In previous studies, the association of MMP8 rs3740938 with the risk of breast cancer has been explored." (PMID 38031100, 2023). "Relevant studies have concluded that the polymorphisms of MMP8 are associated with the risk of a variety of cancers, including breast cancer, thyroid cancer, and laryngeal squamous cell carcinoma." (PMID 38031100, 2023). "Loss of MMP-8 in the MMTV-PyMT transgenic mouse model of human luminal breast cancer promoted tumor onset, growth, and lung metastasis, illustrating the suppressive roles of MMP-8 in tumor progression and metastasis in breast cancer." (PMID 36741729, 2022). "Another study on breast cancer showed an association between MMP8 levels and the levels of metalloproteinase inhibitor 1 (TIMP-1) and MMP9 but not with tissue plasminogen activator, urokinase or their inhibitor (PAI-1)." (PMID 31514474, 2019). "Staining of breast cancer cases for MMP-8 revealed a statistically significant loss of MMP-8 expression in DCIS with invasion versus pure DCIS (p = 0.001)." (PMID 28330493, 2017). "In this aggressive mouse model of breast cancer, loss of MMP-8 accelerated tumor onset even further, such that 90% of MMTV-PyMT; Mmp8-null female mice were tumor-bearing at the time of weaning." (PMID 25848906, 2015). "We have intercrossed Mmp8-null mice with the Polyoma virus middle T oncogene-driven (MMTV-PyMT) mouse model of mammary cancer to explore the effects of loss of MMP-8 on the incidence and progression of mammary carcinomas." (PMID 25848906, 2015). "A C/T single nucleotide polymorphism in the MMP8 promoter that affects MMP-8 expression has been linked to survival of breast cancer patients with early-stage disease, with the high expression T allele equating to better survival." (PMID 23632023, 2013). "Higher MMP8 RNA levels in primary breast cancers are associated with reduced lymph node metastasis and with improved relapse-free and overall survival in node-negative patients." (PMID 23632023, 2013). "Most studies performed in breast cancer associate MMP8 with a protective role." (PMID 38017545, 2023). "For instance, although MMP8 expression has been linked to poor prognosis in liver and gastric cancers, it surprisingly has a protective effect against metastatic progression in head and neck, skin, and breast cancer." (PMID 38017545, 2023). "MMP8 rs1940475 is associated with the risk of breast cancer and gastric ulcer." (PMID 38031100, 2023). "Interestingly, the MMP8 insulator element impairment leads to a decrease in the pro-invasive enzyme MMP1 and increased MMP8 expression levels, two events that are associated with antitumor activity in breast cancer." (PMID 38017545, 2023). "In addition, the T allele of MMP8 C-799 T variant was reported to be related to breast carcinoma susceptibility and lymph node metastasis among Asian and Caucasian population." (PMID 31638929, 2019). "One group reported that the MMP8 C-799 T variant might be related to breast carcinoma susceptibility and lymph node metastasis in Asians and Caucasians." (PMID 31638929, 2019). "The first exception is with MMP-8 where in breast cancer, reduced expression was associated with enhanced metastasis of tumor cells and in null mice, increased susceptibility to skin tumor development was observed with reduced MMP-8 expression." (PMID 24670365, 2014). "Recent work has shown that a SNP in MMP8 may be a predictor of lung cancer risk, and that higher plasma levels of MMP8 may protect against lymph node metastasis in breast cancer." (PMID 21226949, 2011). "Interestingly, we found that MMP8 may affect the metastatic behaviour of breast cancer cells and may be implicated in directing organ-specific metastasis." (PMID 18366705, 2008).